IL2 (interleukin 2)
Diseases named in the same sentence as IL2 in open-access papers (continued):
Sharing a sentence is not in itself a finding about the gene and the disease.
infection (continued). "Additionally, another study has shown that older children, compared to their younger counterparts at the same stage of infection, have reduced levels of pro-inflammatory cytokines like TNF-α, IL-2, and IL-6, as well as Th1-biased chemokines." (PMID 41194029, 2025). "Compared to the traditional treatment, low-dose IL-2 treatment is effective without increased infection incidence." (PMID 40337274, 2025). "Infection with T. gondii activates inflammatory molecules—Interferon gamma (IFN-γ), Interleukin-2 (IL-2), and Tumor necrosis factor alpha (TNF-α)—which upregulate tryptophan-2,3-dioxygenase (TDO) and indoleamine-2,3-dioxygenase (IDO) while leading to degradation of tryptophan into kynurenine." (PMID 40868805, 2025). "At 24 h post-ex vivo infection, the median percentage differences in cytokine levels were as follows: IL-2 and IL-4 both showed no change at 0%; IL-10 exhibited a significant increase at 104%; TNF-α at 167%; and IFN-γ at 197%." (PMID 39456722, 2024). "Compared to the non-infection group, we observed elevated levels of the majority of measured cytokines (25/48) in the CSF during Mtb infection, including TNF-α, IFN-γ, IL-1β, IL-2, IL-3, IL-6, IL-8, IL-10, IL-12(p40), IL-17A, IL-18, IP-10, MIG, MCP-3, MIP-1α, and MIP-1β." (PMID 38047697, 2024). "Notably, the pulmonary levels of several cytokines and chemokines exhibited a secondary increase at days 21 or 28 post-infection (MIP-1⍺, MCP-1, IL-7, IL-10, IP-10, IL-2, and GM-CSF)." (PMID 39066335, 2024). "Finally, the secretion of IL-2 and IFN-γ cytokines showed a discreet decrease trend after infection in some subjects." (PMID 38812507, 2024). "In our experiments, an increase of IL-2–producing immune cells was recorded by flow cytometry analyses after Lt-P10 + LPS + Nig infection of WT THP 1dM cells; it is known that IL-2 is involved in controlling inflammation by inhibiting Th17 cells and IL-6 receptor." (PMID 38707903, 2024). "Another limitation of the study is the impossibility of assessing long-term immunity and protection, as we do not have a follow-up cohort through time after infection to assess possible reinfections according to its IL-2 status." (PMID 38212416, 2024). "Although these factors play important roles in the progression of HIV disease, we speculate that this may be because IL2 and IL6 are markers of HIV early infection, while LTNPs and VPs in our study have lived with HIV for a longer time." (PMID 38799426, 2024). "At 72 h post‐infection, these cytokine/chemokine levels shifted with significantly lower IFNγ and IL‐4, significantly higher IL‐5, IL‐10, IL‐17a, and CCL‐5/RANTES, and comparable IL‐2 and TNFα levels." (PMID 37990641, 2024). "The limiting of autocrine IL‐2 production and the simultaneous de‐repression of IL‐2 signaling suggests that ZFP36L1 enforces dependence of CD8 T cells on paracrine IL‐2, which becomes available during the early phase of an infection and is largely produced by antigen‐specific CD4 T cells and DCs." (PMID 38039407, 2024). "Symptomatically infected children also showed lower S+ MBCs and T cell responses at month 3 as demonstrated by lower secretion of IFNγ and IL-2 in the cytokine release assay than those without symptomatic infection." (PMID 38689059, 2024). "Collectively, these data suggest that SARS-CoV-2-specific IL-2-and IFN-γ + IL-2-producing T cells play a fundamental role in the longevity of cellular and humoral immunity against SARS-CoV-2 vaccination or infection not only in the general population but also in allogeneic HCT recipients." (PMID 38842630, 2024). "Furthermore, we observed a significant increase in TNFα, IL-1α, IL-2, IL-3, IL-4, IL-9, IL-10, IL-12 (P70), IL-17A, and CCL5 on day 4 post-infection in murine macrophages." (PMID 39038037, 2024). "Moreover, Flot2CD4 mice had increased TNF-α+IFN-γ+IL-2+ multifunctional CD4+ T cells, which play a crucial role in infection control." (PMID 39499901, 2024).
infection (continued). "The average serum levels of Th1 cytokines (IL-2 and IL-12) at 0 to 28 dpi were not significantly different among the four groups, regardless of infection or pregnancy statuses." (PMID 36939322, 2023). "Probably these existing CD4+TRMs may secrete IFN- γ and IL-2 upon SARS-CoV-2 infection and recruit CD8+ T cells into the site of infection for virus clearance." (PMID 36851616, 2023). "We infected C57BL/6 mice intranasally with PR8, and 10 days after infection, we performed IFN-γ and IL-2 ELISpot assays with cells from individual spleens and pooled mediastinal lymph nodes (medLNs) stimulated with overlapping peptide pools spanning the whole protein." (PMID 37711622, 2023). "Finally, we detected equivalent levels of IL-2, IFN-y, TNF-α, IL-12, IL-17, IL-22, IL-23, TGF-β, and IL-10 in the lungs of anti-Gr1-treated and control mice during the chronic phase of infection." (PMID 36776848, 2023). "At 4 weeks post-infection, we observed a significant increase in lung infiltrating IL-2, IFN-γ, TNF-α, and IL-17 secreting CD4 but not CD8 T cells in the vaccinated group." (PMID 37359562, 2023). "Data collected 2 h after infection indicated that macrophages infected with Y. pestis pre-incubated with anti-LcrV 7.3 mAb (IgG1) significantly upregulated G-CSF, LIF, MIP-1β, TNF-α, MIP-1α, MCP-3, and MIP-2, while IL-2 and IL-28 were downregulated." (PMID 37289480, 2023). "The expression of the pro‐survival molecules CD127 and Bcl2 was examined in EYFP+ cytokine negative CD4 T cells and those expressing IFN‐γ, IL‐2 or TNF 40 days post‐infection." (PMID 37490492, 2023). "In conclusion, the results of this study suggest that Mhy induces a mixed Th1/Th2 immunity in non-vaccinated animals, and promotes Th1-response, by means the overexpression of IL-2, IL-12, and IFN-γ in vaccinated animals, which was related with protection against the infection." (PMID 36766408, 2023). "In contrast, greater production of IL-4, IL-13, IL-9, and IL-2 was observed following drug treatment irrespective of infection status, consistent with the observation of increased Th2 populations at the PDTB stage." (PMID 37898618, 2023). "At week 4 post infection, CD4+ T-cells showed a mixed response to S. mansoni AWA by secreting cytokines which encompassed Th1 (IFNγ, TNFα, IL-2 & IL-1β), Th2 (IL-4, IL-5, IL-13) and regulatory responses (IL-10) as well as the regulatory T cell transcription factor Foxp3." (PMID 37837930, 2023). "Th1 cytokines, such as IL-2, IFN-γ, and TNF-α, have been previously reported to be stimulated by GSH in uninfected macrophages and are responsible for the activation and cell recruitment of macrophages to the site of infection." (PMID 37507915, 2023). "Surprisingly, both types of NEIs were rarely found in noninfected, PHA/IL-2-activated T cells, whereas the number of cells harboring type II, not type I, NEIs increased after 3- or 6-h infection, indicating that the infection stimulates NEI formation." (PMID 37563144, 2023). "In the study of infection in non-pregnant women, the virus increased certain cytokine levels, such as IL-6, IL-2, and IFN-g." (PMID 37376620, 2023). "Treatment with IL-2 may boost virus-specific CD8+ T-cell responses and stimulate natural killer cell activity against infection." (PMID 36327917, 2023). "In addition, although the transcription of various cytokines, such as IL-1β, IL-2, IL-4, IL-8, and IL-10, was shown to be highly upregulated to defend the organism against DHAV-(1/3) infection, the variation of duck IL-22 after DHAV infection is still unclear." (PMID 37391858, 2023). "Moreover, the levels of IL-2 and IFN-γ secreted by splenic lymphocytes were significantly increased, and the ability of anti-infection of mice was significantly enhanced." (PMID 37355637, 2023).
infection (continued). "The results showed that the protein concentration of inflammatory cytokines in both types of mice was significantly increased after BMA8 strain infection, and the expression of cytokines was higher in BALB/c mice, including IL-2, IL-4, IL-6, IL-10, IL-12p70, KC/GRO, IFN-γ and TNF-α." (PMID 37081549, 2023). "For example, ginseng polysaccharide has demonstrated the ability to elevate interleukin-2 (IL-2), interleukin-8 (IL-8), and tumor necrosis factor-alpha (TNF-α) levels, activating Th1 cell-mediated anti-infection immune responses and enhancing immune regulation in the body." (PMID 38035069, 2023). "On the other hand, gonadectomy increased the IL-2 concentration in males compared to females without infection, resulting in a dimorphic pattern." (PMID 37628731, 2023). "For instance, increased periodontal pathogen abundance will enhance the stimulation of TLRs, induce Th1 to secrete IL-2, IFN-γ, TNF-α to kill intracellular infection pathogens, and then induce Th2 to secrete IL-4, IL-5, IL-6, IL-13 to regulate humoral immunity and limit Th1 response." (PMID 35254118, 2022). "Logistic regression analysis on the results obtained for the training cohort identified three promising combinations of markers to be used to rule-out infection: HBHA- and ESAT-6-induced IFN-γ, HBHA- and ESAT-6-induced TNF-α, HBHA-induced IL-2 and ESAT-6-induced TNF-α." (PMID 35359958, 2022). "A. actinomycetemcomitans infection of implants caused a significant increase in the systemic expression of IL-2, IL-3, IL-5, CCL-3/MIP1α, and CCL2/MCP-1 compared to tissue infections without implants." (PMID 35203495, 2022). "Finally, the ileum cytokines IL-2, IL-12p70, IL-13, IL-17, GM-CSF, IFN-γ, TNF-α, and IL-33 remained unchanged relative to baseline over the course of infection in both genotypes." (PMID 35985797, 2022). "Exactly why IL-2 is a better discriminator than IFN-γ can be answered by a potential bystander effect, where high levels of IFN-γ are produced in unstimulated cells at D28 and D90 post infection." (PMID 35772216, 2022). "Overall, these data indicate that infection with R5/X4 HIV-GKO in the presence of IL-15 or IL-2 does not change the distribution of CD4+ T lymphocytes." (PMID 35499323, 2022). "Th1 cells are known to mediate host defense against pathogens via secreting IFN-γ and IL-2, and CD8+ T effector cells could defeat infection by the production of IFN-γ, perforin, and granzymes." (PMID 36290395, 2022). "The current study observed a decrease in the systemic expression of IL-2 with single or dual species infections with or without implants." (PMID 35203495, 2022). "The dKO OT-I cells showed higher frequencies of KLRG1+ SLEC in blood of the recipients on day 5 post infection irrespective of their ability to produce autocrine IL-2." (PMID 35477960, 2022). "After infection, IFN-γ, mainly produced by NK cells and CD4+ T cells, stimulates macrophage activation, inducing high level of Th1 proinflammatory cytokines (e.g., IL-12, IL-2, IL-18, IL-27) and low levels of anti-inflammatory molecules." (PMID 36060742, 2022). "Both IL-2 and IFN-γ were significantly decreased after infection with ncp BVDV and cp BVDV viruses." (PMID 36366463, 2022). "Next, we analyzed the distribution of six CD4+ T cell subsets (naive, TSCM, TCM, TEM, TTM, and Temra) stimulated with IL-15 or IL-2 in the presence or the absence of R5/X4 HIV-GKO infection." (PMID 35499323, 2022). "Under secondary infection or antigen re-stimulation, TSCM could differentiate into TCM, which mainly secrete interleukin-2 (IL-2); TCM can differentiate into TEM and Teff, and then secrete cytokine interferon-γ (IFN-γ)." (PMID 35493466, 2022). "Within the first 7 days of infection, WT cells out-paced the expansion of Adrb2-/- cells, which correlated with reduced expression of IL-2 and the IL-2Rα in the absence of ADRB2." (PMID 35944008, 2022).
infection (continued). "For instance, HAVCR2 involved in NFAT dephosphorylation was not significantly regulated in MA08 infection and was accompanied by upregulation of IL2 and downregulation of NFATC2 (nuclear factor of activated T cells, cytoplasmic 2)." (PMID 34671358, 2021). "The difference in the effect of PD-1 blockade on lymphocyte proliferation and IL-2 production in CP and NCP BVDV infection may be related to the different effects of the two viruses on the ERK pathway after infection." (PMID 34552590, 2021). "Infection with γHV-68 alone induced expression of multiple cytokines, including IL-27, IL-23, IL-12, IL-6, and IL-2, while stimulation with kyn alone failed to increase cytokine expression." (PMID 33491663, 2021). "The results demonstrate an augmented percentage of IL-2+ CD4+ T cells on day four after infection compared to days 0 or 21 with or without stimulation with anti-CD3 mAb." (PMID 34869064, 2021). "Percentages of IFN-γ−TNF+IL-2+ double-positive multifunctional CD4 T cells were significantly increased in vaccinated C57BL/6 mice after polyclonal restimulation at weeks 2 and 3 post-infection." (PMID 34351501, 2021). "After polyclonal restimulation, frequencies of IFN-γ+TNF+IL-2+ triple-positive multifunctional CD4 T cells were enhanced in vaccinated C57BL/6 mice when compared to the unvaccinated C57BL/6 animals at weeks 2 and 6 post-infection." (PMID 34351501, 2021). "The observed increase in IL-2 and IL-10 production, concomitantly with a reduction in IFN-γ and IL-17 levels on the 19th day of infection, could indicate expansion of Treg cells as already described in response to C. albicans." (PMID 34575795, 2021). "To further determine whether this CD2-mediated inhibition of HIV-1 early infection steps can be alleviated by lymphatic cytokines, we cultured resting CD4 T cells in IL-2 or IL-7 for 3 days and then latently infected cells with HIV-1." (PMID 34765923, 2021). "In a search for immune parameters able to discriminate between primary and remote infections, it was reported that at 180 d after infection onset, CD4+ lymphoproliferation and IL-2 producing HCMV-specific CD8+ T cells were the best parameters for discriminating between PI and remote infection." (PMID 34442828, 2021). "In contrast, in the infected control group, IL-2, IL-4, IL-6, and IL-17a levels rose slowly and did not change significantly after day 21 post-infection." (PMID 33717108, 2021). "Analysis of relative expression over the 5 time points of infection revealed significant upregulation of TNFα, IL1β and IL2 at 28dpi, compared to the brain of non-infected PBS controls." (PMID 34899715, 2021). "The mechanism involved in IL-2 deprivation is this particular group of lymph nodes is not clear but can be associated to the differential distribution of Tregs, since IL-2 could be produced in normal levels and be sequestered by these cells in secondary lymphoid organs during infection." (PMID 32983098, 2020). "HTLV-1-infected T cells, if not all, in ATL patients and the people with HTLV-1-infection were able to proliferate continuously expressing IL-2Rα in the presence of IL-2, but not in the absence IL-2." (PMID 32210945, 2020). "Downregulation of IL-2 in lactobacilli-treated birds suggests immunomodulatory properties of these bacteria in the absence of an infection." (PMID 32185187, 2020). "Having a look at the CD4+IFNγ+TNFa+IL-2+ triple producers, a drastic increase with age was visible independent of infection history (right)." (PMID 32849561, 2020). "These conclusions were supported by the RNA-seq results, indicating that TLRs are not in a main role in recognizing OAd.TNFa-IL2 infection and in facilitating microenvironmental changes." (PMID 32225009, 2020). "There was an over 11-fold increase in the expression levels of IL-2 and TNFa during infection as compared with noninfected SK-MEL-28 cells." (PMID 32225009, 2020).
infection (continued). "This incapability is seen not only upon stimulation of cells with Salmonella antigens but also upon activation with anti-TCR antibody suggesting that the effect of infection on IL-2—producing ability is not restricted to antigen—specific T cells." (PMID 32269573, 2020). "Subsequently, we sought to examine the influence of Ss infection on the systemic levels of Type-1 (IFN-γ, TNF-α, and IL-2), Type-17 (IL-17A and IL-22), Type-2 (IL-4, IL-5, and IL-13), regulatory (IL-10) and pro-inflammatory cytokines (IL-1α, IL-1β, IL-6, IL-12, and GM-CSF) in INF and UN individuals." (PMID 33042134, 2020). "Many studies on intracellular pathogens have shown that the simultaneous production of IFN-γ, IL-2, and TNF-α by multifunctional CD4+ T cells may correlate with protection from infection." (PMID 33105734, 2020). "Both Th1 and Th17 T cells expressed TNFα and IL-2, but then progressed to also express IFNγ at day 7 post infection (which show day 14 post infection in both vaccinated and nonvaccinated mice having received a dose of 103, or even 102 IFUs)." (PMID 31993218, 2020). "The rAAV-IL2 mediated IL2 release resulted in a higher frequency relative to controls of NK cells at bacterial inoculation but not later during the infection." (PMID 32111171, 2020). "Luminex measurement of serum cytokines showed the typical delayed Th1 (IFN-γ, IL-2, and IL-12p40) and an absence of Th2 response (type II cytokines below detection limits) along the course of infection, reminiscent of the observation in patients." (PMID 30944315, 2019). "The levels of interferon (IFN)-γ, interleukin (IL)-2 and neutralizing antibody in the 15-week-old ducks were higher than in the 55-week-old ducks at the early stage of the DTMUV infection, suggesting the immune response in the younger ducks to DTMUV was stronger than in the older ducks." (PMID 31387589, 2019). "The levels of GM-CSF and IL-2 were significantly raised in overall ESRD population as well as those non-diabetic ESRD participants at 6 h post-infection." (PMID 31875015, 2019). "In particular, neutralizing antibodies, induced by ZIKV vaccines, may block infection, while CD4+ and CD8+ T cells secrete IFN-γ, IL2 (Th1), IL-4, and IL-5 (Th2) cytokines to further promote antibody production or directly kill infected cells." (PMID 31717890, 2019). "This study demonstrated that infection with Mtb activates an antigen-specific, polyfunctional Th-1 response as the magnitude of PPD-specific IFN-γ+ IL-2+ TNF-α+ polyfunctional CD4+T-cells was greatest in the LTBI group (P = 0.0002) in comparison with the HC group." (PMID 31105706, 2019). "Immunization and/or infection did not alter cytokines IL-2, IL-4, IL-10, IL-17, IFN-γ, and TNF-α levels; however, IL-6 significantly (p < 0.05) increased, as compared with untreated control." (PMID 31065302, 2019). "Our previous study described that co-infected Ss infection with active or latent TB has significantly reduced Type 1 (IFN-γ, TNF-α, and IL-2), Type 17 (IL-17A and IL-17F) and increased regulatory as well as Type 2 (IL-4, IL-5, and IL-13) cytokines when compared to TB infection alone." (PMID 30897083, 2019). "Even with low levels of IL-2, a major cytokine secreted and responsible for activation of T-cytotoxic cells, an increase in effector Tcyt (CD8+ CD44+ CD62L−) cells was observed in the Junbo mouse middle ear due to NTHi infection." (PMID 31548315, 2019). "Asymptomatic infections were sought by either a combination of PCR, immunofluorescent antibody titre, and direct agglutination tests, or by whole blood stimulation assay (WBA) with interleukin-2 (IL-2) quantification." (PMID 31164191, 2019). "With the exception of IL-2, cytokine production increased with infection regardless of the presence or absence of CD8+ T cells." (PMID 31608052, 2019).